PSEN1 (presenilin 1)
Diseases named in the same sentence as PSEN1 in open-access papers (continued):
Sharing a sentence is not in itself a finding about the gene and the disease.
infectious disease (1 paper, 2022). A disorder directly resulting from the presence and activity of a microbial, viral, or parasitic agent in humans. "In this manner, PSEN1 mutations may have been positively selected as protection against the enormous mortality of infectious diseases." (PMID 35260199, 2022). "PSEN1 variants lead to excess of amyloid-beta, which may function as anti-microbial protein and may have protected against the massive mortality due to infectious diseases during the conquest and colonization of the Americas." (PMID 35260199, 2022).
movement disorder (1 paper, 2020). Neurological conditions resulting in abnormal voluntary or involuntary movement, which may impact the speed, fluency, quality and ease of movement. "EOFAD patients with PSEN1 variants showed early AD onset, frequent visuospatial dysfunction, movement disorders, and rapid disease progression." (PMID 32103039, 2020).
neurogenetic disease (1 paper, 2024). "Among the four, PSEN1 and PSEN2 are known AD-related genes, reported in AlzGene, while C9orf72 and SOD1 are known to be relevant to neurogenetic disease and possess AD-relevant literature support in GeneCards." (PMID 38627848, 2024).
PSEN1 also shares sentences with these, for which no sentence is quoted: late-onset Alzheimers disease (5 papers); retinitis pigmentosa (3); skin cancer (3); Aphasia (2); autism spectrum disorder (2); CADASIL (2); Cerebellar ataxia (2); cognitive disorder (2); Dystonia (2); lung adenocarcinoma (2); myopia (2); Pick disease (2); triple-negative breast carcinoma (2); adenoma (1); age (1); age-related macular degeneration (1); agnosia (1); Alzheimer disease 3 (1); amnesia (1); amyloid‐positive (1); aneurysm (1); arteriolosclerosis (1); autism (1); autoimmune disease (1); autoimmune encephalitis (1); bacterial infections (1); calcification (1); cerebral autosomal dominant arteriopathy with subcortical infarcts and leukoencephalopathy (1); cerebral small vessel disease (1); cerebrovascular disease (1).
A further 53 diseases each share a sentence with PSEN1 in 1 paper.